STAT1 (signal transducer and activator of transcription 1)
Diseases named in the same sentence as STAT1 in open-access papers (continued):
Sharing a sentence is not in itself a finding about the gene and the disease.
colorectal cancer (continued). "This study examined 736 colorectal cancer patients for the expression of STAT1 protein in tissue specimens, including 614 early stage patients and 122 advanced stage patients." (PMID 32275681, 2020). "The tumor suppressor function of STAT1 in colorectal cancer development and progression has been established." (PMID 30235866, 2018). "Previous studies showed that STAT1 expression is a biomarker of favorable prognosis in colorectal cancer." (PMID 28881828, 2017). "Increased expression of STAT1 has been reported to be a favorable prognostic factor in colorectal cancer." (PMID 24324931, 2013). "Additionally, IDO1-expressing Paneth cells, influenced by STAT1 in colorectal cancer, can promote immune escape by modulating the tumor load through immune cell infiltration." (PMID 40909948, 2025). "However, a study in colorectal cancer cells has shown that the IFN-γ/STAT1 signaling promotes MHC-I gene expression by upregulating the expression of WHSC1, which interacts with NLRC5, enhancing H3K36me2 modifications of MHC-I genes." (PMID 40909948, 2025). "Given that GBP2 could mediate STAT1 signaling in both colorectal cancer and renal cell carcinoma, we supposed that GBP2-STAT1 axis might be critical for regulating the tumor immune status in a variety of malignancies." (PMID 37784054, 2023). "In addition, EEF1A1 has been reported to control cell proliferation and cell cycle via activating MAPK signaling in colorectal cancer or STAT1 signaling in hepatocellular carcinoma." (PMID 37446017, 2023). "Such down regulation, which was observed in melanoma and colorectal cancer, is associated with increased metastatic propensity and with the generation of an immune-privileged TME; (ii) perturbations to JAK/STAT1 signaling including epigenetic silencing and inactivating mutations in JAK1." (PMID 33668131, 2021). "STAT1 expression and clinicopathological features of early stage colorectal cancers." (PMID 32275681, 2020). "To examine whether cytoplasmic STAT1 expression is an independent prognostic factor in MSI subtype early stage colorectal cancer, we performed univariate and multivariate analyses." (PMID 32275681, 2020). "The lack of STAT1 predisposed the mice to increased incidence of colorectal cancer showing epithelial cell proliferation and decreased apoptosis during the cancer development." (PMID 32991625, 2020). "Given the complex functional network of STAT1 in cancer biology, it is premature for us to speculate on the precise roles of STAT1 in colorectal cancer or the MSI subtype at present." (PMID 32275681, 2020). "Since our results suggest that STAT1 is a poor prognostic marker for MSI colorectal cancer, we investigated whether its expression correlated with any of the four standard MSI markers currently used in clinical diagnostics." (PMID 32275681, 2020). "We examined whether there was a correlation between STAT1 expression and PD-L1 or PD-1 expression in colorectal cancer." (PMID 32275681, 2020). "Interestingly, the kinetics of caspase-11 upregulation following LPS and IL-1β stimulation closely correlate with those of STAT1 activation, supporting the notion that indirect STAT1 activation requires caspase-11 in colorectal carcinoma cells." (PMID 30538296, 2019). "It is important to note that the report by Crncec and colleagues demonstrated sex-specific tumor suppressor and anti-tumor immune roles for another Stat, Stat1, in colitis-associated colorectal cancer in male but not female mice." (PMID 30389925, 2018). "Thus, our study indicates that high IL-35 levels in colorectal cancer promotes the increased production of IL-35 via STAT1 and STAT3 and results in the suppression of T cell proliferation, leading to tumor immunotolerance." (PMID 27682874, 2016).
colorectal cancer (continued). "Thus, our study indicates that the high level of IL-35 observed in colorectal cancers promotes its own production via STAT1 and STAT3 to suppress T cell proliferation during tumor immunity." (PMID 27682874, 2016). "Furthermore, high STAT1 activity in human colorectal carcinoma specimens was recently identified as a favourable clinical prognosis." (PMID 26391193, 2015). "However, the mechanisms through which STAT1 might prevent colorectal cancer progression preceded by chronic inflammation are still unclear." (PMID 34299314, 2021). "Thus, STAT1 signaling may represent a potential target for therapeutic intervention during the initial stages of colorectal cancer." (PMID 30235866, 2018). "Thus, our study indicates that the high level of IL-35 in colorectal cancer promotes the production of IL-35 via STAT1 and STAT3, which suppresses T cell proliferation and may participate in tumor immunotolerance." (PMID 27682874, 2016). "Although the exact mechanism by which STAT2 promotes colorectal cancer remains to be determined, there is some mechanistic evidence that STAT2 can act outside the canonical IFNAR1-STAT2/STAT1/IRF9 axis via unphosphorylated STAT2." (PMID 41440237, 2025). "FOLR1 is frequently overexpressed in solid tumors, where it promotes proliferation, invasion, and poor prognosis; for instance, in colorectal cancer, FOLR1 upregulation facilitates immune evasion via lactate-induced STAT1 lactylation to suppress MHC-I." (PMID 41439026, 2025). "Recent research utilizing murine lung and colorectal cancer cell lines reveals that Cyclin G2, a specific protein, is integral to the expression of the macrophage IFN-γ/JAK/STAT1/CXCL9 pathway." (PMID 40909948, 2025). "Evidence indicates that the expression of IFI35 in murine colorectal cancer cells is regulated by IFN-γ, with dependencies on STAT1 and IRF-7, thus establishing the IFN-γ/JAK/STAT1/IRF7/IFI35 pathway." (PMID 40909948, 2025). "In colorectal cancer, research indicates that IFITM3 expression is modulated via the IFN-γ/STAT1 pathway, which plays a significant role in immune escape by influencing the stability of regulatory T (Treg) cells and the maintenance of immune homeostasis." (PMID 40909948, 2025). "For example, they reduce the immunosuppression of Treg cells within the colorectal cancer environment by inhibiting the expression of IDO1, which is controlled by signal transducer and activator of transcription 1 (STAT1)." (PMID 39135729, 2024). "Using the online database, we also found that HDAC6 was positively correlated with the downstream target genes of STAT1 or NF-κB p65, such as MYC, RELA (p65) and BCL2L1, in colorectal cancer specimens." (PMID 38231305, 2024). "We then examined clinical data from colorectal cancer (CRC) patients to investigate the potential antagonist effect of CBX3 and IFNγ on the expression of STAT1/PD-L1 in CRC." (PMID 38684864, 2024). "For instance, STAT1-mediated lncRNA LINC00174 overexpression promoted the proliferation and invasion regarding colorectal carcinoma cells via regulating the miRNA-1910-3p/TAZ axis." (PMID 33654226, 2022). "Proteomic analyses indicate that STAT1 protein (signal transducer and activator of transcription 1 or transcription factor ISGF-3 components p91/p84) is upregulated in some colorectal cancers." (PMID 32275681, 2020). "For instance, overexpression of STAT1 increased the expressions of lncRNA LINC00174, resulting in the enhanced ability of cellular growth and metastasis in colorectal carcinoma." (PMID 32396871, 2020). "The role of STAT1 and STAT3 for colorectal carcinoma (CRC) development and progression is controversial." (PMID 27191495, 2016). "On the contrary, research into the IFN-γ/JAK/STAT1/IFIT2 pro-apoptotic pathway has uncovered that AJUBA, with increased expression in colorectal cancers, may induce tumor progression by specifically binding to the FERM domain of JAK1." (PMID 40909948, 2025).
colorectal cancer (continued). "Although it remains uncertain whether this involves activation of the IFN-γ/STAT1 pathway, it suggests that combining CD47 and PD-L1 antibodies after colorectal cancer radiotherapy could enhance therapeutic effects and improve patient survival." (PMID 40909948, 2025). "In colorectal cancers, the epigenetic regulator CBX3 has been shown to inhibit IFN-γ signaling through its binding to the promoters of STAT1 and PD-L1, thereby modulating the chronic inflammatory response-mediated tumorigenesis and mitigating therapeutic resistance." (PMID 40909948, 2025). "However, it is imperative to note that the IFN-γ/JAK/STAT1/IRF-7/IFI35 pathway, as characterized in this study, has yet to be directly validated in vivo within a mouse model of colorectal cancer." (PMID 40909948, 2025). "Similarly, in pMMR-MSI-L colorectal cancer, METTL14 promotes YTHDF2-dependent degradation of Stat1/Irf1 mRNA, dampening IFN-γ–Stat1–Irf1 signaling and limiting CD8+ T-cell activity, which restricts PD-1 immunotherapy response." (PMID 41164187, 2025). "In Affymetrix primeview human GeneChip array, we found six upregulated genes (STAT1, ATF2, TNFRSF10B, TGFBR2, BAX, and SQSTM1) and two downregulated genes (SLC4A7 and CD274) related to apoptosis and proliferation of colorectal cancer cells after hsa_circ_0064559 knockdown." (PMID 37280630, 2023). "METTL3 depletion promotes STAT1 and IRF1 mRNA expression in an m6A-YTHDF2-dependent manner, which in turn improves immunotherapeutic response by modulation of tumor-infiltrating cells in the intratumor microenvironment of colorectal cancer." (PMID 35197058, 2022). "However, in contrast to a previous report, a study demonstrated that only STAT1 and STAT3 were activated by IL-35 expressed by tumor-infiltrating Tregs in colorectal cancer during the induction of iTr35 cells." (PMID 35420296, 2022). "However, based on the positive correlation between STAT1 and PD-1/PD-L1 expression in MSI colorectal cancers found in this study, it is possible that STAT1 plays a pro-oncogenic role in MSI colorectal cancers." (PMID 32275681, 2020). "In contrast to cytoplasmic STAT1, nuclear expression did not correlate with survival in early stage colorectal cancer irrespective of microsatellite status." (PMID 32275681, 2020). "In colorectal cancer, phosphorylated CTD interacting factor 1 (PCIF1) modulates colorectal cancer growth and response to anti-programmed cell death 1 (PD-1) in a context-dependent mechanism in which PCIF1 directly targets FOS, IFITM3, and STAT1 via N6,2′-O-dimethyladenosine (m6Am) modifications." (PMID 40681213, 2025). "Upregulation of DDLPS MDM2 by GP130 signal transduction may be facilitated by STAT1 and STAT3 transcription factors, as seen in colorectal cancer where GP130 activation by IL6 cytokine family member leukemia inhibitory factor led to increased MDM2 levels in a STAT3-dependent fashion." (PMID 40961077, 2025). "Moreover, in colorectal cancer, miR-150-5p inhibits tumor progression by targeting VEGFA; members of the STAT proteins, STAT1, STAT3, and STAT5, have been attested as regulators mediating the expression of VEGFA, involving the mechanisms of angiogenesis as well." (PMID 38737443, 2024). "In colorectal cancer, SPP1+ macrophages highly express complement component 1C chain (C1QC), mannose receptor C type 1 (MRC1), signal transducer and activator of transcription 1 (STAT1), and peroxisome proliferator-activated receptor gamma (PPARG), which are associated with macrophage polarization." (PMID 38919629, 2024). "For example, in colorectal carcinoma and squamous cell carcinoma of the esophagus, STAT1 is associated with a good prognosis, which is not the case for STAT2, probably because STAT1 has multiple effects on cell cycle inhibition by the regulation of p21, p27, and the cyclin D1/Cdk4 complex." (PMID 33076315, 2020).
lung cancer (85 papers, 2011 to 2026). A malignant neoplasm involving the lung. "The loss of STAT1 has been observed in lung cancer tumours and cancer patients exhibiting high STAT1 expression tend to have better clinical outcomes." (PMID 36579897, 2023). "Previous studies have shown that Oct4 and Stat1 are overexpressed in lung cancer; however, their roles and underlying mechanisms are unclear." (PMID 34685622, 2021). "Additionally, we demonstrated in our murine lung cancer model and our human patient cohort that increased expression of STAT1 is associated with decreased tumor size." (PMID 30647851, 2018). "Based on in vitro studies, both rWISP-1 and CM from CAFs or hCAFs exposed to apoptotic lung cancer cells induced STAT1 phosphorylation specifically in M2 macrophages, triggering apoptosis and phenotypic reprogramming." (PMID 41522359, 2026). "It inhibited ferroptosis, a non‐apoptotic cell death mediated by STAT1, and inhibited lung cancer cell proliferation." (PMID 40916076, 2025). "CircKIAA1797 binds to the signal transducer and activator of transcription 1 (STAT1) protein to inhibit the expression of lipoyltransferase 1 (LIPT1) in lung cancer cells." (PMID 40710359, 2025). "Clinically, high expression levels of STAT1 and ETS1 are associated with poor survival outcomes in lung cancer patients." (PMID 40948762, 2025). "Here, we discovered that a specific isoform of type I protein arginine methyltransferases (PRMT), namely, PRMT1, enables lung cancer cells with EGFR or KRASG12C driver mutations and high STAT1 activity to persist through targeted drug treatments." (PMID 39699269, 2025). "Our study identified PRMT1 as the key type I PRMT isoform mediating persistence in STAT1-high lung cancer." (PMID 39699269, 2025). "Generally, suppressing the STAT1/IDO1-mediated tryptophan-kynurenine pathway is regarded as an important strategy of QFM combined with PD-1 inhibitors against lung cancer." (PMID 38882349, 2024). "Elevated levels of leptin can potentially accelerate the progression of obesity-related lung cancer through the activation of the STAT1- solute carrier family 7 member 11 (SLC7A11) pathway, which mediates ferroptosis." (PMID 37943609, 2023). "In support of these findings, blocking IFN signaling by genetic ablation of Stat1 in the KrasG12D-driven lung cancer mouse model resulted in a significantly increased overall survival in comparison to control KrasG12D mice." (PMID 37258521, 2023). "A study reported that the blockade of EGFR by afatinib resulted in decreased STAT1 and IRF-1 levels, and disabled the IFN-γ-STAT1-mediated PD-L1 axis in vitro and in vivo for oral cancer and lung cancer." (PMID 37759950, 2023). "A previous study showed MVP inhibited IFN-γ-mediated activation of STAT1 phosphorylation and nuclear translocation in lung cancer cells." (PMID 38264642, 2023). "The fold change in expression showed significant upregulation for the genes BCL3, CD44, PPARD, POSTN, and STAT1 in lung cancer patients compared to asthmatics." (PMID 35406434, 2022). "The other genes, CD44, PPARD, and STAT1, were also observed to be highly upregulated in lung cancer samples compared to asthmatics and healthy controls." (PMID 35406434, 2022). "In particular, the genes BCL3, CD44, PPARD, and STAT1 showed an increase in expression among the mixed group (asthmatics diagnosed with lung cancer) and lung cancer samples." (PMID 35406434, 2022). "For example, genes such as IRF5 and STAT1 are downregulated in lung cancer cells after infection by viral RNA29, similar to PDX tumor groups with high murine virus load in our analyses." (PMID 33795676, 2021). "The levels of STAT1 and STAT2 mRNAs mirrored the kinetic trajectories observed for other IFN Hallmark genes in the osimertinib-treated lung cancer cell lines but were especially marked in H1650 cells." (PMID 34001994, 2021).
lung cancer (continued). "The overexpression and activation of STAT1 were observed in several human cancers and overexpression of STAT1 acquired chemoresistance and radioresistance in breast and lung cancers by suppressing the cytotoxic response and inducting prosurvival genes." (PMID 31936239, 2020). "In another study, RAs secrete interferon-α (IFN-α) and tumor necrosis factor (TNF), which activates the STAT1 and NF-κB pathways in lung cancer cells residing in the brain." (PMID 33262947, 2020). "Then, we employed GEPIA program to analyze the expression of these 16 TFs using TCGA data, and found that only FOXP3 and STAT1 were significantly highly expressed in lung cancer specimens." (PMID 32396871, 2020). "Then, we searched “GEPIA”, finding that FOXP3 and STAT1 levels were distinctly upregulated in lung cancer." (PMID 32396871, 2020). "In osteoblasts, it has been shown that down‐regulation of STAT‐1 or STAT‐3 reduces the expression of CCL‐234 and in a lung cancer cell line, STAT‐1 was linked to IL‐8 expression, whereas TNF‐α synthesis is regulated via NFκB signalling." (PMID 32374474, 2020). "Meanwhile, KHSRP and HNRNPC can interact with each other and activate the IFN-α-JAK-p-STAT1 signaling pathway, which ultimately increases the invasion and metastasis of lung cancer cells." (PMID 31775888, 2019). "Expression of S100A4, PCNA and c-fos were reduced in STAT1- and STAT1-CC-expressing lung cancer cells, while PCNA and c-fos were decreased to a greater extent in STAT1-CC cells." (PMID 26351076, 2015). "The levels of both proteins were decreased in STAT1 and STAT1-CC transduced lung cancer cells, but there was a greater reduction of β-catenin in STAT1-CC cells." (PMID 26351076, 2015). "The results show that STAT1-CC exhibited more strength in improving the antitumor response of IFNs in lung cancer cells." (PMID 26351076, 2015). "For instance, HDAC4 was shown to activate STAT1 leading to platinum resistance in ovarian cancer patients-derived cell lines and resistance to etoposide in lung cancer cells." (PMID 26206152, 2015). "In this study, STAT1 and STAT1-CC genes were successfully overexpressed in lung cancer cells using the lentivirus-mediated gene transfer system." (PMID 26351076, 2015). "More importantly, STAT1- or STAT1-CC-expressing lung cancer SPC-A-1 cells showed increased levels of apoptosis compared to parent and EGFP expressing cells when treated with either IFN-γ (10,000 U/ml) or IFN-β (10,000 U/ml) for 96 h." (PMID 26351076, 2015). "STAT1-CC has stronger IFN induced antitumor activity than STAT1 through enhanced STAT1 phosphorylation in lung cancer cells." (PMID 26351076, 2015). "In conclusion, overexpression of STAT1 or STAT1-CC inhibits human lung cancer cell proliferation, migration and invasion, and enhances the antitumor response of IFNs in vitro." (PMID 26351076, 2015). "Signal Transducer and Activator of Transcription 1 (STAT1) or a modified STAT1 (designated STAT1-CC) that is hyper-responsive to IFN were overexpressed in lung cancer SPC-A-1 and H1299 cells using lentiviral vectors." (PMID 26351076, 2015). "To examine the effect of STAT1 or STAT1-CC on the migration and invasiveness of lung cancer cells, we performed migration and invasion assays using transwell chambers." (PMID 26351076, 2015). "In order to overexpress wild type STAT1 and STAT1-CC mutant in lung cancer cells, we inserted these cDNA containing IRES-EGFP sequences into a lentiviral vector, and at the same time set up EGFP alone as a control using the same vector." (PMID 26351076, 2015). "STAT1-CC exhibited a stronger inhibitory effect on migration and invasiveness compared with wild type STAT1 in both lung cancer cell lines." (PMID 26351076, 2015). "Whereas it was found STAT3 acted as a JAK1/JAK2-induced oncogenic driver in lung cancers, STAT1 expression was reported to form part of a genetic signature predicting event-free and overall survival of lung cancer patients." (PMID 24833526, 2014).